WWC1 (WW and C2 domain containing 1)
Diseases named in the same sentence as WWC1 in open-access papers (continued):
Sharing a sentence is not in itself a finding about the gene and the disease.
tumor (31 papers, 2011 to 2026). "The Wwc1 gene encodes protein Wwc1 (or KIBRA) that has been reported to suppress tumor growth and metastatic potential in TNBC." (PMID 34836197, 2021). "Studies from Knight and colleagues correlated the loss of the WWC1 locus with the promotion of tumor progression and metastasis in TNBC." (PMID 33467643, 2021). "The study also showed that WWC1 expression was inversely associated with tumor grade and disease stage and hormone receptor‐positive tumors had higher expression than receptor‐negative ones." (PMID 31102318, 2019). "Surprisingly, TAOK1 overexpression in NSCLC promotes tumor cell growth and invasion, which is associated with downregulation of its downstream protein WWC1, and this result might provide a robust research basis to inquire about the precise therapeutic targets for NSCLC." (PMID 36158126, 2022). "Single-cell localization analysis of the risk genes demonstrated that only ADH7, SFN, WWC1, PAK6, and TEAD3 were detectable in the single-cell data, with TEAD3 being predominantly expressed in tumor cells." (PMID 41034991, 2025). "Western blotting results revealed that TAOK1 silencing decreased TAOK1 protein expression and increased WWC1 levels in tumor tissues of rats." (PMID 36158126, 2022). "Since WWC1 was linked to Hippo pathway-dependent cell proliferation and organ size control 10 years ago, interest grew on a putative role of WWC proteins in tumor formation." (PMID 33467643, 2021). "Due to TCF19 inhibition, the tumor-suppressive function of WWC1 is prevented, which, in turn, increases metastasis and malignant progression, depleting the survival rates for CRC patients." (PMID 33467643, 2021). "In several investigations, WWC1 was shown to act as a tumor suppressor, and a disturbed WWC1 expression was often correlated to decreased Hippo pathway signaling and YAP-mediated increase in cell proliferation." (PMID 33467643, 2021). "In summary, the following marker genes were used for subsequent analysis in supratentorial tumours: RELA, ELL3, FBP2, PCP4L1, and MYO3A for detection of RELA+ tumours; and MRAP, IGF1, CAPS, and WWC1 for detection of YAP1+ tumours." (PMID 34314101, 2021). "The 5' gene, WWC1, encodes for a protein KIBRA, a cytoplasmic phosphoprotein that regulates the Hippo/SWH signaling pathway and has been shown to be involved in tumor suppression." (PMID 22032724, 2011). "It is worth mentioning that a ubiquitous Wwc1 knockout in mice causes a mild neurological phenotype but does not lead to organ overgrowth or tumor formation." (PMID 33467643, 2021). "KIBRA (WWC1), a WW and C2 domain-containing protein has been identified as an upstream regulatory component of the hippo pathway (also known as Salvador/Warts/Hippo tumor suppressor network), which regulates cell number by modulating proliferation, apoptosis, and differentiation." (PMID 29523820, 2018). "This review synthesizes current evidence demonstrating that WWC1, WWC2, and WWC3 exert context-dependent effects across malignancies, with WWC2 consistently functioning as a tumor suppressor while WWC1 and WWC3 display tissue-specific variability." (PMID 41727322, 2026). "Certain assays of tumor suppression show a mutual requirement for PTPN14 and WWC1 (KIBRA), but potential contributions of WWC2 and WWC3 in the same assays have not been thoroughly tested." (PMID 38496413, 2024). "Based on this finding, a SuperHippo peptide covering the WWC1/2/3-LATS1/2 interaction interface was thus developed to robustly activate LATS1/2 kinase activity, demonstrating excellent tumor suppression effects in multiple tumor models." (PMID 36924251, 2023). "Recent reports have indicated that WWC1 and WWC2 can function as tumor suppressor molecules in lung cancer." (PMID 33837178, 2021). "Two of the candidates, WWC1-ADRBK2 in HCC3153 cell line and ADNP-C20orf132 in a primary tumor, were confirmed by Sanger sequencing and RT-PCR." (PMID 22032724, 2011).
tumor (continued). "Thus, an miR-21-induced decrease in WWC1 protein promoted cell proliferation, migration and metastasis in LUAD while apoptosis was impeded, resulting in tumor progression." (PMID 33467643, 2021). "WWC1 is often lost in triple‐negative breast cancer and has been shown to suppress tumor metastasis." (PMID 31102318, 2019). "Furthermore, TAOK1 contributed to tumor-promoting effects, manifested by facilitating NSCLC cell proliferation, invasion, and suppressing apoptosis in vitro and accelerating xenograft formation in vivo by reducing WWC1 expression." (PMID 36158126, 2022). "We also did not evaluate whether our tumor samples had a deletion in chromosome 5q which may explain low expression of WWC1." (PMID 31102318, 2019).
cancer (25 papers, 2012 to 2026). A tumor composed of atypical neoplastic, often pleomorphic cells that invade other tissues. "Until today, the association of WWC1 and cancer formation has been confirmed in more than 80 publications." (PMID 33467643, 2021). "Considering the structural similarities and putative redundant functions of all three WWC protein family members, WWC2 and WWC3 are supposed to play a WWC1-comparable role in human cancer." (PMID 33467643, 2021). "Atypical PKC (aPKC), one the first identified binding partners of WWC1, represents a crucial regulator of cell polarity and intracellular transport processes and is frequently overexpressed and activated in many cancer types." (PMID 33467643, 2021). "In contrast, other studies revealed a correlation between an increase in WWC1 expression in distinct human cancer types, pointing to a more pro-proliferative role of the protein." (PMID 33467643, 2021). "Studies report that TCF19 could promote cell proliferation and contribute to the malignant progression of cancer through mechanisms such as regulating WWC1, inhibiting FOXO1, or activating the ATK/FOXO1 signalling pathway." (PMID 38579171, 2024). "Subsequently, we focused on a group of six candidate genes (Cd74, Lpl, Ifi44, Sat1, Fzd9 and Wwc1) that have been reported to be frequently regulated by epigenetic mechanisms and participate in the regulation of important signal pathways during cancer development and progression." (PMID 34836197, 2021). "Initially, studies addressed the impact of WWC1 in human cancer, trying to uncover the involved pathways, specific protein interactions, regulation mechanisms and possible target points for new anti-cancer therapies." (PMID 33467643, 2021). "Although its function in non‐neuronal cells is less clear, emerging evidence suggests that WWC1 may play a role in cancer." (PMID 31102318, 2019). "Besides, WWC1 has been proved to have vital role in various cancers." (PMID 33996611, 2021). "However, the data about the role of WWC1 in cancer are contradictory." (PMID 33467643, 2021). "Nevertheless, the published data revealed that despite a putative redundant function, genomic deletions (such as WWC1 in BC) or disturbed expression of an individual WWC family member is sufficient to decrease Hippo signaling and force cancer formation." (PMID 33467643, 2021). "This review has been designed to provide an update on the published data linking WWC1, WWC2 and WWC3 to cancer, with a focus on Hippo pathway-dependent mechanisms." (PMID 33467643, 2021). "However, due to its high structural similarity to WWC1 and a comparable expression pattern, WWC2 is supposed to fulfil a regulatory role in the Hippo signaling pathway and human cancer, too." (PMID 33467643, 2021). "Although the function of WWC1 has been studied intensively in cells and animal models, our understanding of the expression, biological behaviour and molecular mechanisms of action of WWC2 remains limited, particularly in human cancer." (PMID 28815883, 2017). "A hepatocyte-specific KO of Wwc1 and Wwc2, but not of a single WWC protein, leads to liver overgrowth and subsequent carcinoma formation in mice." (PMID 33483469, 2021).
hematopoietic cancer (1 paper, 2021). "As YAP and TAZ are dispensable for physiological and malignant hematopoiesis, WWC1 function in hematopoietic cancer is likely Hippo pathway-independent." (PMID 33467643, 2021). "The role of WWC1 in hematopoietic cancer is poorly elucidated." (PMID 33467643, 2021).
movement disorder (1 paper, 2025). Neurological conditions resulting in abnormal voluntary or involuntary movement, which may impact the speed, fluency, quality and ease of movement. "Recessively inherited cases with consistent neurodevelopmental and movement disorder phenotypes similar to CP were identified for four genes (HSPA12A, SLC7A1, TP53BP1, WWC1)." (PMID 41282771, 2025).
WWC1 also shares sentences with these, for which no sentence is quoted: cognitive decline (6 papers); dementia (5); B cell acute lymphocytic leukemia (4); clear cell renal cell carcinoma (4); hepatocellular carcinoma (4); neurodegenerative disease (4); cognitive deficit (3); triple-negative breast carcinoma (3); depression (2); hippocampal atrophy (2); leukemia (2); lung carcinoma (2); neuroblastoma (2); Sepsis (2); aging (1); brain injury (1); cervical squamous cell carcinoma (1); delirium (1); developmental delay (1); end-stage renal disease (1); endometrial cancer (1); focal segmental glomerulosclerosis (1); Glomerular sclerosis (1); glomerulopathies (1); Huntington disease (1); infection (1); lymph node metastasis (1); memory impairment (1); metastasis (1); metastatic prostate carcinoma (1).
A further 15 diseases each share a sentence with WWC1 in 1 paper.